PPP1R14A (protein phosphatase 1 regulatory inhibitor subunit 14A)
Description:
Inhibitor of PPP1CA. Has over 1000-fold higher inhibitory activity when phosphorylated, creating a molecular switch for regulating the phosphorylation status of PPP1CA substrates and smooth muscle contraction.
Synonyms: CPI-17; CPI17; PPP1INL
Tractability: PROTAC: its protein half-life has been measured.
Gene: Protein-coding gene on chromosome 19 (38,251,237 to 38,256,557, reverse strand). Ensembl gene ENSG00000167641.
Subcellular location: Cytoplasm
Subcellular location (Human Protein Atlas): Nucleoplasm; Nuclear bodies
Pathways (Reactome):
Signal Transduction: RHO GTPases activate PKNs
Gene Ontology:
Molecular function: protein serine/threonine phosphatase inhibitor activity
Cellular component: nucleoplasm; cytosol; cytoplasm
Genetic constraint (gnomAD): Loss-of-function variants: 12 observed, 12.03 expected, observed/expected ratio (o/e) 1, 90% interval 0.64 to 1.6. The synonymous counts are far from expectation, so gnomAD's model fits this gene poorly and the ratio says little. Missense variants: 208 observed, 155.16 expected, observed/expected ratio (o/e) 1.34, 90% interval 1.2 to 1.5. Synonymous variants: 93 observed, 61.92 expected, observed/expected ratio (o/e) 1.5, 90% interval 1.27 to 1.78.
Homologues: Orthologues: chimpanzee PPP1R14A (100% identical), macaque PPP1R14A (99% identical), pig PPP1R14A (90% identical), mouse Ppp1r14a (85% identical), rat Ppp1r14a (85% identical), guinea pig PPP1R14A (72% identical), dog PPP1R14A (71% identical), rabbit PPP1R14A (71% identical), tropical clawed frog ppp1r14a (48% identical), zebrafish ppp1r14ab (48% identical), zebrafish ppp1r14aa (44% identical), Drosophila melanogaster CG17124 (21% identical), and 1 more. Paralogues in human: PPP1R14C (37% identical), PPP1R14B (34% identical), PPP1R14D (27% identical).
Diseases named in the same sentence as PPP1R14A in open-access papers:
PPP1R14A is named in the same sentence as 40 diseases in open-access papers, as found by Europe PMC text mining. Sharing a sentence is not in itself a finding about the gene and the disease. The quoted sentences say what the papers report.
melanoma (5 papers, 2012 to 2025). A malignant, usually aggressive tumor composed of atypical, neoplastic melanocytes. "Studies have shown that PPP1R14A plays a crucial role in the onset and progression of various tumors, including sporadic vestibular glioma, human melanoma, and schwannoma." (PMID 40406253, 2025). "PPP1R14A was shown in human pancreatic and melanoma tumor cell lines to positively regulate Ras/MAPK signaling, which are also involved in IL-4 induced signaling cascades." (PMID 23110343, 2012).
gastric cancer (4 papers, 2013 to 2022). A primary or metastatic malignant neoplasm involving the stomach. "MTSS1 and DSP are known tumor suppressor genes and are together with PPP1R14A, also methylated in lung-, colorectal- and gastric cancer." (PMID 24260260, 2013). "In addition, the gene PPP1R14A, which is regulated by promoter region methylation, has been proven to play a key role in the initiation and progression of gastric cancer, colorectal cancer, and lymphomas." (PMID 34199440, 2021). "PPP1R14A, also known as CPI-17, has been investigated as a prognostic biomarker of gastric cancer." (PMID 34771544, 2021).
cervical carcinoma (3 papers, 2016 to 2025). A carcinoma arising from either the exocervical squamous epithelium or the endocervical glandular epithelium. "To investigate the role of key genes in cervical cancer survival prognosis, we comprehensively analyzed the correlation between the expression levels of EFNA1, CXCL8, and PPP1R14A, and various clinical features, including age, stage, tumor grade (T), lymph node status (N), and metastasis status (M)." (PMID 40406253, 2025).
Hypertension (3 papers, 2015 to 2021). The presence of chronic increased pressure in the systemic arterial system. "PPP1R14A is a typically upregulated gene in obesity-related hypertension." (PMID 34440281, 2021).
asthma (2 papers, 2022 to 2024). "Through intersections with the validation dataset, we finally identified PPP1R14A as an eosinophil‐associated shared biomarker, which was found to be overexpressed in asthma and downregulated in CC compared to normal tissues." (PMID 39659035, 2024). "Further bioinformatic analysis revealed that PPP1R14A is an eosinophil‐associated shared biomarker in asthma and CC, which is the first discovery reported publicly." (PMID 39659035, 2024). "Through nonpair and pair verification analyses using TCGA data of CC, PPP1R14A was found to exhibit significant expression differences in both CC and asthma and was identified as an eosinophil‐associated hub shared gene." (PMID 39659035, 2024). "By using the LASSO algorithm, we identified five shared eosinophil‐associated hub genes (PPP1R14A, FNBP1, DRAM1, FSCN1, and MMP12) in asthma and CC." (PMID 39659035, 2024). "In asthma, oxidative phosphorylation, protein export, DNA replication, glycolysis gluconeogenesis, and butanoate metabolism were highly enriched in the PPP1R14A low expression group." (PMID 39659035, 2024). "In addition, we explored the molecular mechanism between asthma and CC for the first time and identified that PPP1R14A is a potential therapeutic target and an eosinophil‐associated biomarker for patients with CC." (PMID 39659035, 2024). "Additionally, the lysosome pathway was enriched in the PPP1R14A low expression groups in both CC and asthma." (PMID 39659035, 2024).
lymphoma (2 papers, 2013 to 2021). A malignant (clonal) proliferation of B- lymphocytes or T- lymphocytes which involves the lymph nodes, bone marrow and/or extranodal sites. "The DNA methylation biomarker panel consisting of DSP, FZD8, KCNH2, and PPP1R14A was positive in 89% (54/61) of all lymphomas." (PMID 24260260, 2013). "However, this is, to the best of our knowledge, the first time DSP, FZD8, KCNH2, MTSS1, and PPP1R14A have been reported to be methylated in lymphoma." (PMID 24260260, 2013).
bladder cancer (1 paper, 2025). "While research on PPP1R14A in CESC is limited, studies have shown that its high expression in bladder cancer (BCA) is associated with poor prognosis, suggesting its potential as a prognostic biomarker." (PMID 40406253, 2025).
breast carcinoma (1 paper, 2022). "Lower levels of S26 phosphorylation of PPP1R14A were observed in breast cancer, colon cancer, LUAD, ovarian cancer, and UCEC samples compared to normal samples." (PMID 35656324, 2022). "In addition, S103 phosphorylation of PPP1R14A was significantly decreased in breast cancer and colon cancer compared to normal adjacent tissues." (PMID 35656324, 2022). "In our study, we examined alterations in PPP1R14A phosphorylation levels between primary tumor tissues and normal tissues with the CPTAC database, which includes six types of cancer, namely, breast cancer, KIRC, colon cancer, LUAD, ovarian cancer, and UCEC." (PMID 35656324, 2022).
cervical squamous cell carcinoma (1 paper, 2025). A squamous cell carcinoma arising from the cervical epithelium. "Time-dependent ROC analysis evaluated the prognostic accuracy of a three-gene signature (EFNA1, CXCL8, PPP1R14A) for cervical squamous cell carcinoma survival outcomes." (PMID 40406253, 2025). "A prognostic nomogram integrating three molecular markers (EFNA1, CXCL8, PPP1R14A) with clinicopathological parameters (age, TNM stage) was developed to predict 3-/5-/8-year overall survival in cervical squamous cell carcinoma." (PMID 40406253, 2025).
cognitive deficits (1 paper, 2015). "In a separate study, another regulatory inhibitor subunit, Ppp1r14a expression, was found to be increased in aged-unimpaired mice, which have limited cognitive deficits similar to aged EE mice." (PMID 26102285, 2015).
colon cancer (1 paper, 2022). "Decreased S103 and S109 phosphorylation as well as S107 and S109 phosphorylation in PPP1R14A were observed in colon cancer, respectively." (PMID 35656324, 2022). "Moreover, S109 phosphorylation of PPP1R14A was remarkably decreased in ovarian cancer and colon cancer compared to normal adjacent tissues." (PMID 35656324, 2022). "T38 phosphorylation of PPP1R14A was decreased in colon cancer tissues compared to normal tissues." (PMID 35656324, 2022).
lung carcinoma (1 paper, 2022). "The expression level of PPP1R14A, in addition to the phenomenon of significant positive correlation in OV, negatively correlated with TMB in several tumors, including BLCA, BRCA, COAD, KIRP, LIHC, lung carcinomas, PRAD, SARC, SKCM, and STAD." (PMID 35656324, 2022).
rectal carcinoma (1 paper, 2025). A malignant epithelial neoplasm that arises from the rectum and invades through the muscularis mucosa into the submucosa. "Similarly, PPP1R14A is linked to poor prognosis across cancers, including rectal carcinoma, and correlates with immune cell infiltration." (PMID 40650042, 2025).
renal carcinoma (1 paper, 2022). A carcinoma arising from the epithelium of the renal parenchyma or the renal pelvis. "PPP1R14A and TAGLN exhibit high and extensive synchronization in a variety of malignant tumors, especially renal carcinomas, implying that the two molecules are likely to work together, to indicate tumorigenesis." (PMID 35656324, 2022). "The correlation of the PPP1R14A expression with MSI was also investigated in 33 types of cancer, and it indicated that BRCA, HNSC, and THCA exhibited positive correlations, while COAD, ESCA, renal carcinomas, SARC, and STAD exhibited negative correlations." (PMID 35656324, 2022).
uterine carcinosarcoma (1 paper, 2022). A usually aggressive malignant neoplasm arising from the uterine corpus and less often the cervix. "The frequency of PPP1R14A genetic changes including genetic mutations and copy number alterations (CNAs) in uterine carcinosarcoma reached 16.07%, and these alterations brought misfortune to the survival and prognosis of cancer patients." (PMID 35656324, 2022). "In current study, we investigated the pan-cancer alterations of PPP1R14A using the cBioPortal (TCGA, Pan-Cancer Atlas) database and demonstrated that the alteration frequency of PPP1R14A was 2.3% across 32 various cancers and was prominent, 16.07% in samples of uterine carcinosarcoma." (PMID 35656324, 2022).
tumor (16 papers, 2011 to 2025). "PPP1R14A influenced γδ T cells and M2 macrophages (P<0.05), linked to tumor progression." (PMID 40406253, 2025). "EFNA1, CXCL8, and PPP1R14A emerged as prognostic biomarkers for CESC, showing significant associations with survival, tumor stage, and immune infiltration." (PMID 40406253, 2025). "PPP1R14A was associated with fibroblast growth factor signaling and extracellular matrix (ECM) organization, critical for stromal remodeling and tumor invasion." (PMID 40406253, 2025). "We observed that PPP1R14A had lower expression in CC compared with normal colon tissue, indicating its potential role as a tumor suppressor gene." (PMID 39659035, 2024). "Overall, this research has contributed to understanding the role of PPP1R14A in tumorigenesis from the perspective of clinical tumor samples." (PMID 35656324, 2022). "Four genes, PPP1R3C, PHF21B, TPM1 and PPP1R14A, were highly downregulated in the tumor tissues compared with the normal tissues." (PMID 25789025, 2015). "Interestingly, we found that the expression of PPP1R14A parallels that of CEA during tumor progression." (PMID 39659035, 2024). "Meanwhile, a bioinformatic study indicated a significant correlation between the protein phosphatase 1 regulatory inhibitor subunit 14A (PPP1R14A) expression and the prognosis of patients of diverse tumor types across TCGA cohort, adding to the understanding of our results." (PMID 38659038, 2024). "In addition, PPP1R14A was also evaluated for changes in the degree of methylation and the possibility of becoming tumor markers in other cancers, such as GBM, HNSC, and CRC." (PMID 35656324, 2022). "Furthermore, we observed a gradual increase in PPP1R14A expression with tumor progression in CC." (PMID 39659035, 2024). "Our results demonstrated that the expression pattern of PPP1R14A in cancers represented by ESCA, KIRP, and PCPG has a positive relationship with both ICMs and the infiltration of tumor immune lymphocytes." (PMID 35656324, 2022). "EFNA1 may drive tumor progression via the MAPK signaling pathway, CXCL8 could influence immune evasion through NOD-like receptor signaling, and PPP1R14A may contribute to tumor invasion by modulating extracellular matrix remodeling." (PMID 40406253, 2025). "Overall, the expression trend of PPP1R14A in this tumor is ambiguous, meaning that it does not have the effect of promoting the progress of KIRC." (PMID 35656324, 2022). "The promoters of DSP, FZD8, KCNH2, and PPP1R14A were methylated in 28%, 67%, 22%, and 78% of the 36 tumor samples, respectively, but not in control samples." (PMID 24260260, 2013). "The potential relationship between genetic alterations in PPP1R14A and the prognosis of patients with different types of cancer was investigated, revealing that tumor patients with genetic alterations in PPP1R14A had worse OS, DFS, DSS, and PFS than patients without alterations." (PMID 35656324, 2022).
cancer (10 papers, 2013 to 2025). A tumor composed of atypical neoplastic, often pleomorphic cells that invade other tissues. "To investigate the association between the PPP1R14A expression and clinicopathological features in multiple cancers, we assessed the PPP1R14A expression in cancer patients of stages I, II, III, and IV." (PMID 35656324, 2022). "The distinct relationship between PPP1R14A and the immune response gave opportunity to perform a pan-cancer analysis of the association between PPP1R14A expression and the immune infiltration levels based on TIMER and XCELL algorithms." (PMID 35656324, 2022). "PPP1R14A has shown associations with different cancer types in prior large-scale GWASs, including colon and prostate cancer." (PMID 35173190, 2022). "Complementary qRT-PCR analysis demonstrated significant transcriptional upregulation of oncogenic effectors - EFNA1, CXCL8, and PPP1R14A in carcinoma versus control tissues (P<0.05)." (PMID 40406253, 2025). "In UALCAN, PPP1R14A showed a remarkably low protein expression in all six types of adult cancers tested, these results are consistent with the transcription level analyses." (PMID 35656324, 2022). "The analysis of PPP1R14A provides new insights into the carcinogenic role of PPP1R14A across multiple malignancies and provides further understanding of the individual management for cancer precision therapy." (PMID 35656324, 2022). "The corresponding heatmap exhibits the relationship between PPP1R14A and the two intersecting molecules in the various cancer types." (PMID 35656324, 2022). "The analysis of the prognostic survival of PPP1R14A in various cancers revealed a strange phenomenon, which was inconsistent with the general understanding of the molecule." (PMID 35656324, 2022). "Phosphorylation modification levels regulating cancers progression and PPP1R14A exist various phosphorylation sites." (PMID 35656324, 2022). "For example, in CHOL, HNSC and other malignant tumor samples, the methylation expression profile of the high promoter region of PPP1R14A is related to the high expression level of transcription." (PMID 35656324, 2022). "Next, we evaluated the relationship between PPP1R14A and the prognosis of patients across different cancers." (PMID 35656324, 2022). "In this study, we found that PPP1R14A exhibited consistent mRNA expression in 23 different types of common human cancers, according to the results from the TIMER2.0 database." (PMID 35656324, 2022). "Promoter region hypermethylation is a common mechanism associated with the silencing or inactivation of tumor suppressor genes in cancer cells, which may explain the downregulation of PPP1R14A in CC in our results." (PMID 39659035, 2024). "Moreover, the ROC results indicate that PPP1R14A, whose AUC values surpass 0.9 in multiple malignant tumors such as BLCA, COAD, and KIRP, reached the outstanding level in the diagnostic test evaluation." (PMID 35656324, 2022). "Therefore, deeply examining the regulatory functions and molecular mechanisms of PPP1R14A in pan-cancer is vital to gain new insights into relevant carcinogenic mechanisms and inform strategies and direction for the clinical treatment of cancers." (PMID 35656324, 2022). "However, most studies on the function of PPP1R14A in cancers were restricted to specific cancer types." (PMID 35656324, 2022). "This initial pan-cancer analysis of PPP1R14A showed that PPP1R14A expression was statistically correlated with clinical prognosis, DNA methylation, protein phosphorylation, immune cell infiltration, and ICMs/TMB/MSI in multiple tumors and paves a way ahead for further research." (PMID 35656324, 2022). "Overall, PPP1R14A may likely play completely different roles in the initiation and progression of most cancers, different from our general understanding of the molecule to date." (PMID 35656324, 2022).
cancer (continued). "However, it exhibited a role in promoting cancer progression in patients with these three types of tumors, where upregulation of PPP1R14A promotes the malignant processes of tumors, thereby contributing to lower patient survival probabilities." (PMID 35656324, 2022). "However, there is almost no research forthcoming to reveal the landscape of phosphorylated PPP1R14A in many cancers to date." (PMID 35656324, 2022). "In addition, methylation within the promoter region of PPP1R14A DNA was enhanced in a majority of cancers." (PMID 35656324, 2022). "No cancer-relevant role has so far been reported for the PPP1R14A gene, which encodes a protein phosphatase, and is involved in regulating the contraction in smooth-muscle tissue." (PMID 24260260, 2013). "PPP1R14A emerged as a stromal interface regulator, with GO enrichment in fibroblast growth factor signaling and extracellular matrix (ECM) organization, corroborated by KEGG pathways encompassing ECM-receptor interactions and cancer-associated adhesion molecules." (PMID 40406253, 2025). "Analysis of the relationship between PPP1R14A expression and the PFI of patients across cancers was also conducted." (PMID 35656324, 2022). "The expression of PPP1R14A has a negative relationship with ICMs and immune cell infiltration levels in malignant tumors such as SARC or TCGT." (PMID 35656324, 2022). "Meanwhile, our analysis, broadly explains the PPP1R14A promoter methylation level is significantly altered in BLCA, COAD, KIRP, and other cancers, giving clarity and expectation that the PPP1R14A could become a novel prognostic marker and potential therapeutic target." (PMID 35656324, 2022). "Despite emerging evidence revealing the remarkable roles of protein phosphatase 1 regulatory inhibitor subunit 14A (PPP1R14A) in cancer tumorigenesis and progression, no pan-cancer analysis is available." (PMID 35656324, 2022).
PPP1R14A also shares sentences with these, for which no sentence is quoted: airway hyperresponsiveness (2 papers); colorectal cancer (2); mesothelioma (2); prostate carcinoma (2); schwannoma (2); Sepsis (2); B-cell lymphoma (1); bladder tumors (1); bladder urothelial carcinoma (1); cardiovascular diseases (1); colitis (1); Coronary Artery Spasm (1); glioma (1); heart failure (1); nodular malignant melanoma (1); Obesity (1); ovarian carcinoma (1); pancreatitis (1); pulmonary arterial hypertension (1); Sudden Cardiac Death (1); superficial spreading melanoma (1); urothelial carcinoma (1); virus infection (1).